MC3R (melanocortin 3 receptor)
Diseases named in the same sentence as MC3R in open-access papers (continued):
Sharing a sentence is not in itself a finding about the gene and the disease.
Obesity (continued). "Other gene mutations in heterozygous states (MRAP2, MC3R, SRC1, KSR2) are associated with obesity and may exhibit autosomal dominant inheritance; however, the clinical phenotype depends on the degree of genetic penetrance and interactions with other genetic and/or environmental factors." (PMID 41751424, 2026). "•Complete loss of MC3R function does not result in obesity in humans." (PMID 41386534, 2026). "In 2019, a meta-analysis of published studies suggested that heterozygous loss-of-function (LoF) mutations in MC3R were not likely to be the cause of a penetrant form of dominantly inherited obesity but individuals with obesity were more likely to carry a LoF variant in MC3R." (PMID 41386534, 2026). "While it remains formally possible that some MC3R variants may contribute to increased BMI in certain populations, MC3R should not be considered a monogenic obesity gene and should not feature on diagnostic panels for genetic obesity." (PMID 41386534, 2026). "In humans, rare inactivating MC3R variants have been associated with obesity but not consistently." (PMID 41401256, 2025). "However, it is unclear whether deletion of MC3R specifically regulates the initial acquisition of weight gain on a HFD, or whether deletion of MC3R amplifies weight gain in mice that already exhibit diet‐induced obesity." (PMID 39718394, 2025). "Additionally, mutations in MC3R and MC4R are associated with obesity." (PMID 36358958, 2022). "Though polymorphisms in the MC3R may predispose an individual to obesity, the role of the MC3R has not been clearly elucidated." (PMID 31013889, 2019). "However, the results from the NES-MC3R experiment suggest that the loss of food anticipatory behaviors associated with Mc3r-deficiency is not secondary to obesity, as FAA is restored independently of reductions in FM." (PMID 28294152, 2017). "Although mutations in the MC3R gene may not be involved in autosomal dominant form of monogenic obesity, these mutations could predispose humans to increased risk of obesity." (PMID 25825681, 2015). "The influence of the MC3R gene variants on obesity is not evident." (PMID 24142065, 2013). "The absence of increased obesity or metabolic disease risk in MC3R p.F45S carriers of this study, together with a subcutaneous-biased adipose distribution, suggests that MC3R may influence metabolic health through regulation of adipose tissue distribution rather than overall adiposity." (PMID 42303965, 2026). "It was found that the expressions of ENPP1, MC3R, and SIM1 were significantly different between controls and obesity." (PMID 39351493, 2024). "While early studies of MC3R in rodent models indicated roles for MC3R in energy metabolism, including in food anticipatory responses, and associations between MC3R deletion and mild late-onset obesity without hyperphagia or hypometabolism, other studies produced seemingly contradictory findings." (PMID 36943057, 2023). "We sequenced the MC3R coding region in study groups of 443 children or adolescents, comprising 185 with SNS, 258 with severe obesity (n = 258), and 192 healthy-lean adults as a control group." (PMID 37369769, 2023). "Two genetic knockout models of obesity were discussed, the melanocortin 4 receptor (MC4-R) and melanocortin 3 receptor (MC3-R) knockout mice." (PMID 35054972, 2022). "Similar to MC4R, MC3R was also identified as an important regulator of energy expenditure, with 7 DCVs [BMI SDS=3.3 (2.2)] showing early obesity, albeit with unclear difference between the number of carriers with and without obesity." (PMID 35574020, 2022). "However, MC3R gene polymorphism in humans has not yet been definitively associated with obesity." (PMID 33716796, 2021). "The Mc4r KO and DKO rats generated in our lab will be beneficial for future studies to further elucidate MC3R and MC4R’s function and signalling pathways, and provide better rat models for novel anti-obesity or anti-diabetic drug development." (PMID 27713523, 2016).
Obesity (continued). "In contrast, mice lacking MC3R are not hyperphagic and do not develop severe obesity but have reduced linear growth and an increased ratio of fat to lean mass." (PMID 41386534, 2026). "The dysregulated autophagy observed in Mc3rTB/TB and MC3RhDM/hDM liver is thus not due solely to the obesity phenotype, rather these data indicate a distinct role of Mc3r in autophagy regulation." (PMID 39956805, 2025). "Consistent with this interpretation, rodents and humans with mutations in MC4R are hyperphagic and obese, while MC3R knockout (KO) mice exhibit minor late onset obesity, without noticeable hyperphagia when provided ad libitum access to regular chow diet." (PMID 39718394, 2025). "MC3R and MC4R have been investigated as promising targets for anti-obesity drugs." (PMID 38577975, 2024). "Consequently, we Sanger sequenced the coding region of MC3R in 185 and 258 children and adolescents with SNS or severe obesity, respectively, and 192 healthy lean individuals." (PMID 37369769, 2023). "Unlike the hyperphagia and severe obesity phenotype in Mc4r−/− mice, homozygous Mc3r knockout mice exhibit a mild phenotype, characterized by moderate obesity and no hyperphagia but elevated fat mass and reduced lean mass." (PMID 35955857, 2022). "Mice lacking Mc3r have a moderate obesity phenotype with normal food intake and metabolism, decreased lean mass and increased fat mass." (PMID 36358958, 2022). "Since many questions remain about the relationship between MC3R and obesity, this new non-rodent model will be of great value for future research." (PMID 31138220, 2019). "Targeting the MC3R and MC4R may therefore lead to the development of treatments for metabolic disorders such as obesity, anorexia, and cachexia." (PMID 31013889, 2019). "None of the genotyped variants in genes for monogenic obesity reached genome-wide significance in our GWAS, although several variants in CRHR1, CRHR2, MCHR1, MC3R, MC4R and POMC were nominally associated." (PMID 23251661, 2012). "Thus, it seems clear that the complete absence of MC3R function does not by itself result in a penetrant form of human obesity." (PMID 41386534, 2026). "Interestingly, unlike other monogenic obesity models with defective hypothalamic signaling (e.g., Mc4rKO mice), recent studies suggest Mc3rKO mice develop an obese phenotype in part via MC3R insufficiency outside of the CNS8,23." (PMID 39956805, 2025). "Although MC4R-related obesity is well documented, MC3R-related obesity is not as well studied." (PMID 40001512, 2025). "Thus, MC3R signalling in dMH regulates the initial acquisition of weight gain in response to HFD but does not amplify weight gain following diet‐induced obesity." (PMID 39718394, 2025). "In addition, there was no hyperphagia or glycaemia, indicating that Mc3r KO mice are more protected from metabolic syndrome compared to other obesity models with similar levels of adiposity." (PMID 27713523, 2016). "By contrast to the initial response to novel HFD, dMH deletion of MC3R did not alter feeding or body weight gain when mice were accustomed to HFD and had already developed diet‐induced obesity." (PMID 39718394, 2025). "MC3R and MC4R knockout mice develop obesity while control mice do not, but the obesity phenotype differs between the two knockout variants." (PMID 35328759, 2022).
Anorexia (7 papers, 2009 to 2025). Lack of desire to eat (loss of appetite). "More recently, we demonstrated that the Mc3r–/– mouse exhibit greater anorexia and weight loss than do WT mice in response to behavioral challenges, including restraint and social isolation." (PMID 39007271, 2024). "For example, the Mc3r–/– mouse was demonstrated to exhibit greater anorexia and weight loss in response to LPS treatment or IL-1β treatment and greater loss of both fat mass and lean mass in response to implantation of Lewis lung carcinoma cells." (PMID 39007271, 2024). "Therefore, we next tested whether medial hypothalamic MC3Rs mediate the enhanced anorexia associated with MC3R inhibition." (PMID 39718394, 2025). "Conversely, MC3R KO mice are hypersensitive to various anorexic challenges, including stress‐related anorexia (restraint stress and social‐isolation‐induced anorexia), diverse forms of pharmacological anorexia and physiological anorexia (tumour‐associated anorexia)." (PMID 39718394, 2025). "For example, we have demonstrated that deletion of the MC3R increases sensitivity to anorexia induced by restraint and social isolation." (PMID 39007271, 2024). "Herein, we show that activation of MC3-R ameliorates LPS-induced anorexia and muscle proteolysis by decreasing inflammation as well as the changes in glucocorticoid and IGF-I release, but also through a direct action on muscle cells." (PMID 27177152, 2016). "Importantly, although sex differences exist in the propensity of MC3R deletion to alter energy rheostasis, MC3R deletion consistently results in increased body weight and/or feeding in response to a HFD, and enhanced weight loss and/or anorexia following semaglutide." (PMID 39718394, 2025). "This is consistent with studies showing MC3R-depletion enhances anorexia in mice and indicates that modulating MC3R could be an effective therapy to increase weight gain and reduce anxiety in eating disorders while antagonising the receptor could promote weight loss." (PMID 36943057, 2023). "For example, female MC3R KO mice (but not males) demonstrate an enhanced response to forms of stress‐induced anorexia and reduced sucrose preference that is not observed in male MC3R KO mice." (PMID 39718394, 2025).
Anxiety (7 papers, 2012 to 2025). Intense feelings of nervousness, tension, or panic often arise in response to interpersonal stresses. "MC3R activation has been linked to increased anxiety and stress response." (PMID 35906220, 2022). "Small molecules that act specifically on the MC3R have recently been described, with MC3R agonists shown to increase feeding and reduce anxiety, and MC3R-specific antagonists shown to suppress feeding in mice." (PMID 36943057, 2023). "To date, only MC3R and MC4R with their ligand, the alfa-MSH (also gamma-MSH in the case of MC3R) were connected to anxiety and depression." (PMID 36004833, 2022). "Studies in humans examining the effects of these MC3R agonists and antagonists will be required to assess their effect on multiple parameters including weight, food intake, anxiety, growth, onset of puberty and cardiovascular functions (e.g. blood pressure and heart rate)." (PMID 36943057, 2023). "Gene expression analysis of feeding-related genes (AgRP, NPY, OXT) and those involved in regulating stress and anxiety (DOR and MC3R) were differentially regulated in the VPA rats." (PMID 40004532, 2025). "Notably, feeding-related genes (AgRP, NPY, OXT) and those involved in regulating stress and anxiety (DOR and MC3R) were differentially regulated in the VPA rats." (PMID 40004532, 2025).
Arthritis (4 papers, 2017 to 2025). Inflammation of a joint. "The K/BxN serum transfer model of arthritis was induced in both wild type (WT) and MC3 deficient mice (Mc3r−/−)." (PMID 27853832, 2017). "MC3R knockdown with serum transfer-induced arthritis exacerbated significant bone erosion, high expression of RANKL in the joint, increased time of NF-kB activation, and upregulation of proinflammatory genes [IL-1β, IL-6, and nitric oxide synthase 2 (NOS2)]." (PMID 35874704, 2022). "Other studies also showed similar action via MC3R pathways in experimental arthritis." (PMID 41002740, 2025). "Conversely, overexpression of MC3R and MC3R agonist D [Trp8]-γ-MSH significantly reduced the degree of arthritis, suggesting that MC3R may be an important target in preventing bone destruction and inflammation progression in arthritis." (PMID 35874704, 2022). "All Mc3r−/− mice treated with fenoprofen developed arthritis." (PMID 27853832, 2017).
hyperglycaemia (4 papers, 2016 to 2024). "Interestingly, double knockout Mc3r−/−/Mc4r−/− rats demonstrate even more severe hyperlipidemia and hyperglycemia than Mc4r−/− knockout rats, despite the fact that knocking out the Mc3r gene alone causes hypophagia and fat mass accumulation without necessarily becoming overweight." (PMID 38019584, 2024). "Despite the fact that MC3R and MC4R deficiency showed an opposite effect on food consumption and body weight in our mutant rats, we observed additive effects of Mc3r KO to Mc4r KO in phenotypes including adipocyte size, hepatic steatosis, lipid profile, OGTT and hyperglycaemia." (PMID 27713523, 2016). "For example, unlike Mc3r knockout mice, MC3RhDM/hDM mice, do not exhibit hyperglycaemia in low fat-fed conditions or increased inflammation in WAT in high-fat-fed conditions compared with wild-type mice." (PMID 26818770, 2016).
metabolic syndrome (4 papers, 2015 to 2025). A cluster of metabolic risk factors for CARDIOVASCULAR DISEASES and TYPE 2 DIABETES MELLITUS. "No BS for either KLF14 or SREBF1 was identified in the promoters of MC4R, 5-HT2C, MC3R, S1PR2, FFAR1/GPR40, and HCR2 within this database, despite their known association with metabolic syndrome." (PMID 40243421, 2025). "The anti-inflammatory role of MC3R has also been confirmed in the context of metabolic syndrome in mice knockout for MC3R independently of weight gain." (PMID 37508552, 2023).
Cerebral ischemia (3 papers, 2021 to 2025). Restriction of arterial blood supply to the brain associated with insufficient oxygenation to support the metabolic requirements of the tissue. "Of great clinical importance is also the role of MC3R activation in preventing ventricular tachycardia and fibrillation in myocardial ischemia, as well as MC4R agonism for the treatment and recovery from cerebral ischemia." (PMID 34512392, 2021). "In addition, some studies have shown that the activation of MC3R and MC4R by their endogenous ligands is able to improve the outcome of cardiovascular diseases, such as myocardial and cerebral ischemia." (PMID 34512392, 2021).
diabetes (3 papers, 2012 to 2025). "Although Mc3r -deficient mice were neither hyperphagic nor did they develop diabetes under normal diet, Mc3r mutant mice lost significantly more of their body weight under caloric restriction and gained weight at a much faster rate after energy-rich chow." (PMID 35937837, 2022).
gouty arthritis (3 papers, 2013 to 2025). "Indeed, it was not until 2002 that local activation of melanocortin-3 receptor (MC3R) by ACTH, independent of glucocorticoid, was demonstrated to be also responsible for ACTH efficacy in gouty arthritis." (PMID 31649620, 2019).
Hypertension (3 papers, 2013 to 2021). The presence of chronic increased pressure in the systemic arterial system. "The present data demonstrate that NDP-α-MSH could alleviate sodium retention in the DOCA-salt model of hypertension via MC3-R-mediated diuretic and natriuretic actions." (PMID 23977363, 2013). "However, it is an open question whether pharmacological targeting of the MC3-R could have therapeutic efficacy in experimental models of hypertension." (PMID 23977363, 2013). "Multiple studies reviewed here have highlighted how the central melanocortin system, and in particular the antagonism of the MC3R and MC4R receptors, are able to significantly decrease elevated BP and HR in both lean and obese forms of hypertension." (PMID 34512392, 2021).
myocardial ischemia (3 papers, 2021 to 2025). A disorder of cardiac function caused by insufficient blood flow to the muscle tissue of the heart. "Various studies were conducted to delineate the receptors involved in the protective effect of melanocortin in myocardial ischemia/reperfusion and found that MC3R was the main receptor mediating this effect." (PMID 41002740, 2025).
tuberculosis (3 papers, 2013 to 2023). A chronic, recurrent infection caused by the bacterium Mycobacterium tuberculosis. "Increased expression of the MC3R gene and high levels of MC3R protein in active tuberculosis is associated with its physiological role as a regulator of energy metabolism and the immune system." (PMID 37521838, 2022). "Further research is needed to elucidate the precise role of MC3R and its variants in terms of tuberculosis susceptibility." (PMID 23497691, 2013). "In the promoter region of MC3R the polymorphism rs6127698 has previously been shown to be strongly associated with tuberculosis susceptibility." (PMID 23497691, 2013). "In past examinations, MC3R was related to TB susceptibility, macrophages interceding the host's intrinsic invulnerable reaction against Mycobacterium tuberculosis through microbe acknowledgment and initiation of the fiery reaction." (PMID 37521838, 2022).
Hyperinsulinemia (2 papers, 2015 to 2024). An increased concentration of insulin in the blood. "Mc3r deficient mice are also hyperleptinaemic and male Mc3r−/− mice develop mild hyperinsulinemia." (PMID 25825681, 2015).
obesity syndrome (2 papers, 2012 to 2026). "Deletion of the mouse Mc3r gene causes an obesity syndrome, and some reports indicate that MC3R polymorphisms that impact on signaling may be associated with increased risk of childhood obesity." (PMID 22353545, 2012). "While MC3R deficiency may influence linear growth and body composition, complete loss of MC3R does not result in a penetrant human obesity syndrome." (PMID 41386534, 2026).
pulmonary TB (2 papers, 2008 to 2022). "Studies have shown that MC3R may be involved in the development of inflammatory diseases, such as pulmonary tuberculosis and arthritis." (PMID 37521838, 2022).
cognitive decline (1 paper, 2021). "Instead, the MC1R and the MC3R, which have higher expression levels in the hippocampus than the MC4R and showed statistically significant correlations with the performance of aged rats in spatial learning and memory, may be better drug targets for the aging-related cognitive decline." (PMID 34684847, 2021).
endotoxemia (1 paper, 2022). "The binding of α-MSH to its receptor MC4R/MC3R promotes energy expenditure and weight loss, which are the vital determinants of muscle wasting during endotoxemia." (PMID 35428321, 2022).
Genetic obesity (1 paper, 2025). "Population studies have shown, however, that MC3R-related genetic obesity is widespread in obese adolescent populations." (PMID 40001512, 2025). "Therefore, more structural and protein interaction studies are required to further clarify the roles of POMC-derived neuropeptides, MC3R, and MC4R in genetic obesity." (PMID 40001512, 2025).
glucose metabolic disorders (1 paper, 2016). "Although MC3R deficiency led to a reduction of food consumption and body weight, it did show some additive effects on top of MC4R deficiency in both lipid and glucose metabolic disorders, which suggests different signalling pathways exist for MC3R." (PMID 27713523, 2016).
hypogonadotropic hypogonadism (1 paper, 2023). Abnormal ovarian or testicular function due to insufficient hormonal stimulation from the hypothalamic-pituitary axis. "This work aimed to determine whether deleterious MC3R variants are more frequently found in patients clinically presenting with constitutional delay of growth and puberty (CDGP) or normosmic idiopathic hypogonadotropic hypogonadism (nIHH)." (PMID 37339320, 2023).
inflammatory bowel disease (1 paper, 2025). A spectrum of small and large bowel inflammatory diseases of unknown etiology. "The latest clinical research data indicate that the expression of MC3R and MC5R is significantly increased in inflamed mucosa of inflammatory bowel disease (IBD) patients compared to normal mucosa." (PMID 40078988, 2025).
liver disease (1 paper, 2025). "The restoration of hepatic Mc3r resulted in improvements in adiposity, metabolic dysfunction-associated steatotic liver disease, and insulin sensitivity." (PMID 39956805, 2025).